RNU7-149P (RNA, U7 small nuclear 149 pseudogene)
Gene: Small nuclear RNA gene on chromosome 4 (98,966,815 to 98,966,873, reverse strand). Ensembl gene ENSG00000252548.
Homologues: Orthologues: chimpanzee U7 (98% identical), macaque U7 (92% identical). Paralogues in human: RNU7-57P (83% identical), RNU7-60P (83% identical), U7 (83% identical), RNU7-13P (81% identical), RNU7-82P (81% identical), RNU7-11P (80% identical), RNU7-121P (80% identical), RNU7-171P (80% identical), RNU7-41P (80% identical), RNU7-65P (80% identical), RNU7-67P (80% identical), RNU7-6P (80% identical), and 141 more.